PMS2 (PMS1 homolog 2, mismatch repair system component)
Diseases named in the same sentence as PMS2 in open-access papers (continued):
Sharing a sentence is not in itself a finding about the gene and the disease.
tumor (continued). "Further analysis determined that PMS2 (MMR) and LIG4 (NHEJ), essential components of their respective pathways, were downregulated across multiple cell lines after chronic and acute hypoxic exposure, providing potential targets for re-sensitisation of hypoxic tumour cells to DNA damaging therapies." (PMID 33986995, 2021). "No somatic second hit in PMS2 was detected in the matched tumor sample." (PMID 32295625, 2020). "We initially sought to demonstrate the performance of scPred by making computational predictions of tumor and non-tumor cells based on their transcriptomes and validating our classification using a cell-specific independent immunohistochemistry assay targeting the MLH1 and PMS2 protein expression." (PMID 31829268, 2019). "In addition, the IHC results showed lack of MLH1 and PMS2 in both the whole tumor and spheroids (data not shown)." (PMID 30680068, 2018). "The tumor tissue from patient 14B-ON3619BD1 also showed a negative IHC staining for PMS2." (PMID 28445943, 2017). "Moreover, we also observed an age related dysregulation of APE1, PMS2 and PTEN in adult tumours." (PMID 25026297, 2014). "However it is important to note that PMS2 expression in sporadic paediatric tumours did not influence outcome in the current study." (PMID 25026297, 2014). "Interestingly, we also found that PMS2 expression was negatively correlated with GSK-3β inactivation in tumor tissues, indicating that activated GSK-3β may stabilize PMS2 production directly." (PMID 20178594, 2010). "Tumour cells of MLH1 mutation carriers generally lacked MLH1 and PMS2 protein by IHC staining." (PMID 17453009, 2007).
tumor (continued). "Tumours of MSH6 mutation carriers lacked MSH6, and those of PMS2 mutation carriers lacked PMS2." (PMID 17453009, 2007). "In addition, in our unselected cohort, many PGVs are identified in genes such as BRCA1, MSH6, PMS2, and NF1, which are crucial not only for germline follow-up but also for selecting appropriate therapies, particularly immune-based or targeted treatments, as observed in other tumor types." (PMID 41168197, 2025). "In addition, IHC for PMS2 could not be performed due to the lack of tumour tissue for all patients eligible for analysis." (PMID 26485756, 2015). "In our case, the patient had a dMMR tumor indicated by negative MLH-1 and PMS-2 on immunohistochemical analysis." (PMID 40859488, 2025). "PMS2 and MSH6 were scored manually as “lost” or “present”, without estimating the percentage of negative tumour cells." (PMID 39040241, 2024).
tumor (continued). "All carrier’s tumor samples (III-1, II-5, and II-6) lacked the expression of PMS2 protein and had MSI-H status." (PMID 32197529, 2020). "When MLH1 and PMS2 are absent by IHC, the next step is analysis of BRAF by either PCR or IHC to help determine if the patient has a sporadic tumor or should be further evaluated for LS." (PMID 28259170, 2017). "In addition, 5/6 tumours in carriers were MSI-high and 3/7 tumours lacked expression of PMS2 on IHC." (PMID 39334433, 2024). "In addition, there is functional compensation between MMR proteins (PMS2/PMS1, MSH6/MSH3), which can maintain the tumor MSS status in the absence of the four most frequently detected MMR proteins." (PMID 36591511, 2022).
cancer (423 papers, 2002 to 2026). A tumor composed of atypical neoplastic, often pleomorphic cells that invade other tissues. "Accordingly, the PMS2 gene has been defined as a low-penetrance gene for cancers associated with LS." (PMID 40723192, 2025). "Here, we describe two unrelated patients with a personal and family history of cancer who harbor a novel PMS2 missense variant (c.184G>A; p.Gly62Arg) with uncertain clinical significance." (PMID 40723192, 2025). "In this study, we report the clinical and molecular characterization of a missense PMS2 gene variant (NM_000535.7: c.184G>A; p.Gly62Arg) that was identified in two unrelated patients with a personal and family history of cancer." (PMID 40723192, 2025). "A defective PMS2 gene associated with LS substantially elevates the possibilities of developing specific cancers, particularly CRC and EC in comparison to the general population." (PMID 40452892, 2025). "Ten (91%) SB‐MCs were classified as dMMR, as they showed a combined loss of MLH1 and PMS2 expression by all cancer cells." (PMID 39192803, 2025). "In fact, establishing the pathogenic potential of these variants in patients with a personal and/or family history of cancer remains challenging due to the variable clinical manifestations and lower penetrance associated with the PMS2 gene." (PMID 40723192, 2025). "The third pMMR IHC phenotype was isolated PMS2 loss (~ 10%) which was also responsible for a significant number of discrepancies in all cancers." (PMID 38350968, 2024). "Conversely, LSVH with germline PVs in the MSH6 gene have an increased risk of endometrial cancer and a slightly higher risk of colorectal cancer (CRC), whereas LSVH with germline PVs in the PMS2 gene have a lower risk of developing any cancer." (PMID 39767815, 2024). "Among the cancer-associated proteins we found five hotspot mutations conferring loss (NFE2L2 E79V/Q) or gain (PMS2 R107W, MUTYH S321L, CTNNB1 S33F) of interactions (Dataset EV6)." (PMID 39009827, 2024). "The aim of this study was to describe all PMS2 variants identified, and to describe frequency, spectrum and penetrance of cancers in carriers of class 4/5 variants." (PMID 39334433, 2024). "The large heterozygous deletion of PMS2 (280,707 bp; spanning exons 2 to 15) found in patient 1 has partial homology with the pseudogenes and, therefore, can impact the cancer risk of this patient and her family members." (PMID 37628631, 2023).
cancer (continued). "Immunohistochemical analysis revealed the loss of MutL homolog 1 (MLH1) and postmeiotic segregation increased 2 (PMS2) expression in the cancer cells of biopsied specimens, suggesting deficient mismatch repair (dMMR)." (PMID 37095273, 2023). "It is reasonable to suggest that CNVs of PMS2 contribute to the cancer risk in HBOC and HBCC patients." (PMID 37628631, 2023). "Previous studies have identified biallelic pathogenic PMS2 mutations driven CMMRD leading to cancers in younger patients." (PMID 37296477, 2023). "Recent findings show that, while the cancer risk is relatively low, PMS2-deficient CRCs tend to show more aggressive behaviour and have a worse prognosis than other MMR-deficient CRCs." (PMID 36895471, 2023). "Resulting from partial redundancy, PMS2 deficiency is associated with a relatively low cancer penetrance which makes classification using only clinical criteria extremely challenging." (PMID 35451539, 2022). "Unfortunately, presumably owing to the low cancer penetrance of inactivating PMS2 defects, too few clinically classified (likely) predisposing variants were available to generate a reference set for calibration purposes." (PMID 35451539, 2022). "Predisposing variants in PMS2 confer a low prevalence of cancer due to the protein's genetic redundancy (11%–20% lifetime colorectal cancer risk by age 70)." (PMID 35451539, 2022). "Patients carrying MSH6 PVs have a cancer risk of a little less than 55% by 70 years of age and PMS2 PV carriers are at much lower cancer risk at a little less than 20% at 70 years of age." (PMID 36088367, 2022). "Statistically, the most significant differences in the frequency of P/LP germline variants between patients and population-matched non-cancer controls were detected in PMS2, DNAJC21 (truncating variants only), and MUTYH (OR ranging from 4.1 to 48.9)." (PMID 35739278, 2022). "For MSH6, the risk is 24% for men and 40% for women while the risk of cancer development throughout life varies from 25–32% for carriers of a PMS2 mutation." (PMID 36612072, 2022). "There are two previously published cases of childhood/AYA cancer caused by digenic inheritance of a heterozygous PMS2 PV and a heterozygous POLE exonuclease PV." (PMID 36291559, 2022). "Three cases (27.3%) showed a loss of MLH1 and PMS2 antibody staining, and were classified as dMMR cancers." (PMID 34845844, 2022). "The cumulative incidences of overall cancers for PMS2 pathogenic variant carriers are the lowest among the four pathogenic germline variants, with cumulative cancer incidences of 34.1% at the age of 75." (PMID 34118983, 2021). "Given the high prevalence of the PMS2 c.2002A>G variant among Inuits, generation of a mouse model that mimics this mutation would be a valuable tool in efforts to prevent the early onset cancers occurring in an under-served Canadian population." (PMID 34489406, 2021). "PMS2-related SEOC is less common due to lower risks for these cancers associated with germline PMS2 mutation compared to other Lynch genes." (PMID 34357101, 2021).